KIF5B (kinesin family member 5B)
Diseases named in the same sentence as KIF5B in open-access papers (continued):
Sharing a sentence is not in itself a finding about the gene and the disease.
varicocele (3 papers, 2020 to 2025). A condition characterized by the dilated tortuous veins of the spermatic cord with a marked left-sided predominance. "Among the altered proteins, several exosomal proteins including Annexin A2 (ANXA2), Transferrin (TF), Kinesin‐1 heavy chain (KIF5B), and semenogelin 1 (SEMG1) were found to be consistently expressed differently in the seminal plasma of patients with unilateral varicocele." (PMID 41222141, 2025). "Based on these findings, it has been proposed that KIF5B and ANXA2 could be considered potential biomarkers for exosomal dysfunction in patients with varicocele." (PMID 41222141, 2025).
Ad (2 papers, 2022 to 2023). "Our findings showed that the loss of KIF5B influences the tauopathy phenotype in AD, although it is unclear if restoring the function of KIF5B would have a similar effect." (PMID 36387285, 2022). "Using the SHSY5Y cell model of Alzheimer’s disease, we found that KIF5B plays a crucial role in regulating phospho tau levels." (PMID 36387285, 2022). "To assess tau pathology in the brains of P301S+/− and P301S+/−,KIF5B+/− mice, we used AT8, AT100, AT180, and PHF1 monoclonal antibodies, which are commonly used as diagnostic markers of Alzheimer’s disease." (PMID 36387285, 2022). "Here, we reported that the kinesin-I heavy chain (KIF5B), a key molecular motor protein, is involved in tau homeostasis in AD cells and animal models." (PMID 36387285, 2022). "Collectively, our results suggested that decreasing KIF5B levels is sufficient to prevent and/or slow down abnormal tau behavior of AD and other tauopathies." (PMID 36387285, 2022). "The role of KIF5B-mediated transport in AD also needs to be determined." (PMID 36387285, 2022). "Thus, KIF5B/kinesin-1 is a promising target for the therapeutic intervention of AD and other tauopathies." (PMID 36387285, 2022). "Our in vivo findings highlight the importance of KIF5B, the heavy chain of kinesin 1, in regulating Tau abnormalities and tau-related memory deficits in several tau-related neurodegenerative disorders, including AD." (PMID 36387285, 2022). "To establish the regulatory functions of KIF5B in tau phosphorylation, we first knocked down KIF5B in SHSY5Y-Tau- P301L, an extensively used AD cell model." (PMID 36387285, 2022). "Hence, whether KIF5B is a positive or negative regulator in AD models remains unclear." (PMID 36387285, 2022).
Alzheimer’s disease (2 papers, 2022 to 2023). A progressive, neurodegenerative disease characterized by loss of function and death of nerve cells in several areas of the brain leading to loss of cognitive function such as memory and language. "While these findings suggest that KIF5B might be involved in tau regulation and Alzheimer’s disease (AD), the precise molecular mechanisms through which KIF5B regulates tau degradation remain unclear." (PMID 38275365, 2023).
developmental delay (2 papers, 2023 to 2025). "The KIF5B Leu498Pro and Leu537Pro mutations were found in patients with developmental delay translating in variable symptoms including myopathic features, and localize to the KIF5B coiled-coil domains and likely affects KIF5B dimerization." (PMID 40589526, 2025).
endometrial carcinoma (2 papers, 2024 to 2025). A malignant tumor arising from the epithelium that lines the cavity of the uterine body. "In conclusion, our findings strongly support the integration of EIF4G2, KIF5B and KLC1 markers into clinical practice for the management of endometrial carcinoma." (PMID 38388710, 2024). "Consistent with our findings of KIF1B's inflammatory regulatory role, a previous study demonstrated that KIF5B, a kinesin family member closely related to KIF1B, regulates epithelial–mesenchymal transition through the PI3K/AKT/mTOR inflammatory pathway in endometrial cancer." (PMID 41384344, 2025).
hereditary spastic paraplegia (2 papers, 2023 to 2024). Hereditary spastic paraplegias (HSP) comprise a genetically and clinically heterogeneous group of neurodegenerative disorders characterized by progressive spasticity and hyperreflexia of the lower limbs. "The extensive repertoire of kinesin families, especially the KIF5 family (comprising KIF5A, KIF5B, and KIF5C), stand out as crucial players in anterograde transport, with disruptions leading to neurodegenerative conditions like Alzheimer’s and hereditary spastic paraplegia." (PMID 39507380, 2024).
Hyperglycemia (2 papers, 2013 to 2021). An increased concentration of glucose in the blood. "Our results demonstrated that GAP-43 and KIF5B protein expression between C, DC, DT and T groups was significantly different, demonstrating that GAP-43 and KIF5B protein levels in the rat gastrocnemius skeletal muscle fibers were affected by both ET and hyperglycemia." (PMID 33953268, 2021).
insulinoma (2 papers, 2024 to 2025). "Efficient depletion of KIF5B was achieved by utilizing two independent lentiviral-based shRNA against mouse Kif5b in mouse insulinoma cell line MIN6." (PMID 41182903, 2025). "In this study, we have investigated the molecular roles of KIF5B in beta cells in detail using the beta-cell-specific KIF5B conditional knockout (cKO) mice and KIF5B-knockdown MIN6 insulinoma cells." (PMID 39322740, 2024).
kyphomelic dysplasia (2 papers, 2023 to 2025). "Despite its first description nearly four decades ago, the precise molecular basis of this condition remained elusive until the recent discovery of de novo variants in the KIF5B-related kyphomelic dysplasia." (PMID 39506047, 2025). "Pathogenic variants in KIF5B were previously reported in individuals with kyphomelic dysplasia, a skeletal dysplasia characterized by short stature, narrow thorax, bowing of the long bones and dysmorphic craniofacial features." (PMID 37934770, 2023). "Recently, heterozygous de novo variants in KIF5B have been found to be associated with a kyphomelic dysplasia, while several bent bone dysplasias do not have a known genetic basis." (PMID 39506047, 2025).
liver cancer (2 papers, 2022 to 2024). An epithelial or non-epithelial malignant neoplasm that arises from the liver. "Silencing KIF5B can significantly reduce the proliferation, invasion, and metastasis of liver cancer cells." (PMID 38321105, 2024). "Importantly, we found that circKIF5B circRNA, rather than KIF5B linear mRNA, was notably upregulated in liver cancer cell lines and tissues." (PMID 35847962, 2022). "Importantly, we found that circKIF5B circRNA, rather than KIF5B linear mRNA, was significantly upregulated in liver cancer tissues and cell lines." (PMID 35847962, 2022).
osteogenesis imperfecta (2 papers, 2023 to 2024). Osteogenesis imperfecta (OI) comprises a heterogeneous group of genetic disorders characterized by increased bone fragility, low bone mass, and susceptibility to bone fractures with variable severity. "We identified de novo, heterozygous variants in KIF5B, encoding a kinesin-1 subunit, in four individuals with osteogenesis imperfecta." (PMID 37934770, 2023). "Here, we identified heterozygous, de novo variants in KIF5B in four unrelated individuals with osteogenesis imperfecta, including a recurrent variant p.Thr87Ile that resides in the highly conserved nucleotide-binding P-loop domain." (PMID 37934770, 2023). "We identified de novo, heterozygous missense variants in KIF5B kinesin motor domain in four individuals with osteogenesis imperfecta." (PMID 37934770, 2023). "In summary, we have identified heterozygous variants in KIF5B as a novel cause of osteogenesis imperfecta with a dominant negative mechanism due to an intracellular trafficking defect and downregulation of mTOR signaling pathway." (PMID 37934770, 2023). "We report dominant negative variants in the KIF5B kinesin motor domain in individuals with osteogenesis imperfecta." (PMID 37934770, 2023). "The study identifies KIF5B variants as a novel cause for osteogenesis imperfecta and suggests that mTOR signaling may be potentially targeted for future therapy in KIF5B-related disorder." (PMID 37934770, 2023). "We report here pathogenic variants in KIF5B in individuals with osteogenesis imperfecta." (PMID 37934770, 2023). "More research is needed to determine whether impaired collagen secretion is contributing to the phenotype in KIF5B-related osteogenesis imperfecta." (PMID 37934770, 2023).
osteopetrosis (2 papers, 2017 to 2023). Osteopetrosis, also known as marble bone disease, is a descriptive term that refers to a group of rare, heritable disorders of the skeleton characterized by increased bone density on radiographs. "Kif5B binds to and functions in lysosomal trafficking of Osteopetrosis Associated Transmembrane Protein 1 (Ostm1), a gene associated with osteopetrosis in humans, connecting Kif5B to cartilage/bone development." (PMID 28715414, 2017). "The lack of OSTM1 vesicles linked to KIF5B cargos caused an absence of lysosomes on the ruffled border, resulting in dysfunctional secretion, inefficient bone resorption, and osteopetrosis." (PMID 37106712, 2023).
papillary thyroid carcinoma (2 papers, 2014 to 2016). "TheRET fusion genes discovered in these studies include CCDC6-RET (already known as RET/PTC1 in papillary thyroid carcinoma) as well as a novel fusion with KIF5B (kinesin family member 5B), encoding a coiled coil domain, generated by pericentric inversion in chromosome 10." (PMID 27429741, 2016).
Stroke (2 papers, 2022 to 2025). Sudden impairment of blood flow to a part of the brain due to occlusion or rupture of an artery to the brain. "Regional MSN differences were associated with cortical transcriptional gradients, identifying key stroke-related genes (e.g., KIF5B, C4orf3, APMAP, STOML1)." (PMID 41356252, 2025). "The depletion of KIF5B is neuroprotective in cerebral ischemia preconditioning (a stroke model) in KIF5B heterozygous knockout mice." (PMID 36387285, 2022). "Shared DEGs between AIS and CIS, including genes such as KIF5B, C4orf3, APMAP, and STOML1, may reflect common molecular signatures associated with stroke across different clinical stages." (PMID 41356252, 2025).
tauopathies (2 papers, 2022 to 2024). "We also found that reducing or eliminating KIF5B expression significantly decreased tau levels in both animal and cell models of tauopathy." (PMID 39507380, 2024). "Given that reducing KIF5B in P301S mice partially alleviates tauopathy, it is plausible to consider targeting KIF5B as a viable therapeutic approach for AD and other tauopathies." (PMID 39507380, 2024). "Our study on the in vivo heterozygous knockout of KIF5B in the P301S mouse model of tauopathy showed that a 50% drop in the KIF5B level was sufficient to reduce overall tau levels and rescue the phenotype." (PMID 36387285, 2022).
thyroid (2 papers, 2022 to 2025). "We also evaluated alkynyl nicotinamide RET TKIs in KIF5B-RET-induced lung tumors in immune competent transgenic mice, and in CCDC6-RET fusion-positive thyroid patient-derived xenograft PDX.003.047 tumors." (PMID 40496186, 2025).
amyotrophic lateral sclerosis (1 paper, 2025). Amyotrophic lateral sclerosis (ALS) is a neurodegenerative disease characterized by progressive muscular paralysis reflecting degeneration of motor neurons in the primary motor cortex, corticospinal tracts, brainstem and spinal cord. "Mutations in KIF5A, KIF5B and KIF5C are causes of neurological disorders such as amyotrophic lateral sclerosis (ALS)." (PMID 41290147, 2025).
Bardet-Biedl syndrome (1 paper, 2024). A ciliopathy with multisystem involvement. "Furthermore, genetic interaction studies suggest that the nuclear/cytoplasmic distribution of CCDC28B, a protein associated with Bardet-Biedl syndrome, is influenced by KIF5B, as targeting KIF5B leads to nuclear accumulation of CCDC28B." (PMID 38218748, 2024).
bladder cancer (1 paper, 2022). "Previous studies revealed that kinesin family members [Kinesin family member C1 (KIFC1), Kinesin family member 5B (KIF5B), and Kinesin light chain 1 (KLC1)] play important roles in accelerating epithelial−mesenchymal plasticity in bladder cancer and breast tumors." (PMID 35811688, 2022).
depression (1 paper, 2022). "In particular, we discovered for the first time that RAB1A, GNAI3, RAB33B, LAMP2, and KIF5B might be potential markers for the diagnosis of depression." (PMID 35559009, 2022).
epilepsy (1 paper, 2023). A brain disorder characterized by episodes of abnormally increased neuronal discharge resulting in transient episodes of sensory or motor neurological dysfunction, or psychic dysfunction. "Some of them were already known to play a role in AD: PICK1 is involved in synaptic scaling; AP2A2 is involved in receptor-mediated endocytosis; SYT7 is regulated by amyloid precursor protein; and KIF5B is critical for GABAAR transport, and its deletion causes epilepsy." (PMID 36538112, 2023).
glaucoma (1 paper, 2022). Increased pressure in the eyeball due to obstruction of the outflow of aqueous humor. "Among these, Kif5a showed decreased synthesis when normalized to the total newly synthesized proteome after induction of glaucoma, while Kif5b was relatively unchanged (complete data in)." (PMID 35259089, 2022).
glioma (1 paper, 2025). A benign or malignant brain and spinal cord tumor that arises from glial cells (astrocytes, oligodendrocytes, ependymal cells). "In a follow up study by the same group using C6 glioma cells, 4 of our hits (Tubb1, Tubb5, Actg1 and Kif5b) were present out of a list of 22 enriched proteins." (PMID 41142754, 2025).
infertile (1 paper, 2023). "Another similar study compared seminal exosomal protein levels in fertile versus infertile men and distinguished that within the infertility group, many proteins were differentially expressed, including the upregulation of ANXA2 and the downregulation of KIF5B." (PMID 35980542, 2023).
ischaemia (1 paper, 2024). "While Drp1 facilitates the release of KIF5B from the complex and also plays a role in mitochondrial fission to protect against cardiac ischaemia/reperfusion." (PMID 38951127, 2024).
large cell neuroendocrine carcinoma (1 paper, 2024). A usually aggressive carcinoma composed of large malignant cells which display neuroendocrine characteristics. "The emerging occurrence of KHDRBS1–NTRK3 fusion was observed in a patient with KIF5B-RET fusion + LCNEC (large cell neuroendocrine carcinoma) progressing on selpercatinib." (PMID 39199650, 2024).
medullary thyroid carcinoma (1 paper, 2023). "Exposure of LUAD-0002AS1 (NSCLC, KIF5B–RET), ECLC5B (NSCLC, tripartite motif-containing 33 (TRIM33)–RET) and TT cells (medullary thyroid carcinoma, RETC634W) to vepafestinib resulted in efficient downregulation of RET phosphorylation at Y905 and Y1062 and downstream effectors." (PMID 37743366, 2023).
memory impairment (1 paper, 2022). "By conducting experiments on P301S tau mice, we showed that partially reducing KIF5B levels can reduce hyperphosphorylation of the human tau protein, formation of insoluble aggregates, and memory impairment." (PMID 36387285, 2022).
metastatic diseases (1 paper, 2016). "Given our result that Apatinib inhibits cellular invasion and migration by fusion kinase KIF5B-RET, it may be possible of using Apatinib in tumors harboring RET gene fusions, especially those with metastatic diseases, which needs further animal studies or clinical trials to confirm." (PMID 27494860, 2016).
motor neuron diseases (1 paper, 2022). "We suggest that Kif5b and other kinesin members have the potential to also contribute to the pathogenesis of other motor neuron diseases like SMA." (PMID 36089582, 2022).
neuroblastoma (1 paper, 2019). Neuroblastoma (NB) is the most common solid, extracranial childhood tumor. "KIF5B deficiency does not result in cytokinetic defect in neuroblastoma cells, myogenic cells or pancreatic cells, implying that the molecular motors controlling central spindle organization vary among different cell types." (PMID 31636894, 2019).
Neurodevelopmental delay (1 paper, 2023). "Heterozygous variants in KIF5B, the gene encoding the Kinesin-1 heavy chain, have been implicated in neurodevelopmental delay, skeletal dysplasia, myopathy, and dysmorphic features." (PMID 37934770, 2023).
neuroendocrine tumor (1 paper, 2025). "KIF5B-ALK (K17:A20): This fusion was first identified in a large-cell neuroendocrine tumor." (PMID 40852483, 2025).
osteosarcoma (1 paper, 2009). A usually aggressive malignant bone-forming mesenchymal neoplasm, predominantly affecting adolescents and young adults. "First, we examined the mRNA expression levels of KIF5B in three cancer cell lines(MCF-7, HeLa and U2OS osteosarcoma) and found it to be highly expressed in allthree cell lines when compared to other N-kinesins including KIF5A/KIF5C(Kinesin 1), KIF3A (Kinesin 2) and KIF1A (Kinesin 3)." (PMID 19242560, 2009).
pericardial effusion (1 paper, 2025). Fluid collection within the pericardial sac, usually due to inflammation. "While pericardial effusion analysis in this case successfully identified KIF5B-RET fusion, its utility is constrained by limited availability and potential sampling bias." (PMID 40599544, 2025).
pneumonia (1 paper, 2023). An acute, acute and chronic, or chronic inflammation focally or diffusely affecting the lung parenchyma, caused by an infection in one or both of the lungs (by bacteria, viruses, fungi, or mycoplasma.). "A total of 8 patients with pneumonia were included in the study, most of which were non-smoking female patients and the main fusion gene was KIF5B (87.5%), which was consistent with the general characteristics of RET fusion population." (PMID 37924363, 2023).
sarcoma (1 paper, 2016). A usually aggressive malignant neoplasm of the soft tissue or bone. "Morphologically, tissues were similar to sarcoma tissue, and more mitotic figures and abnormal nuclei could be seen, confirming that KIF5B-RET fusion gene could induce the malignant transformation of fibroblast cell lines of 3T3." (PMID 27494860, 2016).
small cell lung carcinoma (1 paper, 2023). Small cell lung cancer (SCLC) is a highly aggressive malignant neoplasm, accounting for 10-15% of lung cancer cases, characterized byrapid growth, and early metastasis. "After transformation into small cell lung cancer, KIF5B-RET was still present with a abundance of 39.65%." (PMID 38057798, 2023).